IFNG (interferon gamma)
Diseases named in the same sentence as IFNG in open-access papers (continued):
Sharing a sentence is not in itself a finding about the gene and the disease.
tumor (continued). "It is well-known that IFNα, IFNγ and TNFα signaling mediate antitumor immunity whereas TGFβ signaling induces tumor immunosuppression 37-42." (PMID 33767579, 2021). "On the contrary, IFNγ has antitumor effects by both acting on tumor cells directly and remodeling the tumor microenvironment, including function modulation of tumor-infiltrating immune cells and stromal cells." (PMID 34438367, 2021). "Previous studies have highlighted the role of IFNG gene signatures in predicting the tumor responsiveness to the ICB therapy." (PMID 34566988, 2021). "In both melanoma and pancreatic adenocarcinoma cell lines, knockdown of LDHA resulted in increased NK cell proliferation, IFNγ and granzyme B production, and tumor control by immune cells." (PMID 33670082, 2021). "HLA silencing is a common tumor mechanism to evade cellular immunity, with tumors containing IFNγ or “inflamed” tumors conferring an improved prognosis and higher overall susceptibility to immunotherapy approaches such as immune checkpoint inhibitors." (PMID 33968037, 2021). "Both combination therapies increased NKT cell toxicity and were dependent on IFNγ production, demonstrating an increased anti-tumor immune response." (PMID 34680322, 2021). "When NK cells are activated, cytolytic molecules are released to induce apoptosis of tumor cells, and cytokines such as interferon-gamma (IFN-γ) and tumor necrosis factor alpha (TNF-α) are produced to regulate adaptive immune T cell-mediated immune responses." (PMID 34682815, 2021). "Contralateral tumor harvested at 7 days showed significant increase in CD3+CD8+IFNγ+ and CD3+CD4+IFNγ+ T cells over ablation alone and untreated control, while T-regulatory cell population decreased in frequency." (PMID 33668932, 2021). "Interferon-gamma (IFN-γ) released by tumour-reactive infiltrating lymphocytes (TILs) represents a major driver of tumour cell-extrinsic PD-L1 expression and immune escape." (PMID 34740105, 2021). "On the other hand, activation of IFNG signaling pathway in tumor cells can antagonize the function of T cells and innate immune cells." (PMID 34497605, 2021). "MiR-155 has been also shown to regulate adaptive immunity by promoting IFNγ anti-tumor responses by CD4+ and CD8+ T-cells." (PMID 33924670, 2021). "Together, these data demonstrated that HSD-induced tumor immunity is mediated by NK cell and IFNγ production." (PMID 34516769, 2021). "Numerous studies have established the important role of the type II IFN, IFNγ as a key player in host anti-tumor immunity through direct anti-tumor and indirect immunoregulatory actions." (PMID 33842331, 2021). "Dual roles of IFNγ in tumor immunity have been reported, as either a suppressor or promoter of tumor development." (PMID 33406733, 2021). "Ironically, HLA-E expression on tumor cells is induced by interferon-gamma (IFN-γ), which is produced by active immune cells." (PMID 34952595, 2021). "Targeting immune cells is important; indeed, the combination of a CD40 agonist and a PD-1 antagonist MAb exerts anti-tumor effects, which are manifested through tumor infiltration by IFNγ-, Granzyme B-, and TNFα-secreting effector T cells." (PMID 34439378, 2021). "We previously reported that production of interferon gamma (IFNγ), a cytokine with a well-established role in anti-tumor immune responses 11, was significantly activated by T317 through activation of LXR." (PMID 33456564, 2021). "In turn, cytokines secreted by NK cells, such as IFNγ and TNFα as well as NKp30 engagement, support DCs maturation and polarization towards an anti-tumor phenotype." (PMID 34712615, 2021). "IFNγ secretion and the consequent impact on macrophage phenotype was found to be responsible for NK cell-mediated tumor control in the methylcholanthrene (MCA)-induced sarcoma model." (PMID 33546248, 2021).
tumor (continued). "They further outlined an association between cytokine/chemokine expression and immune tumor infiltrates, suggesting that the expression of specific tumor cytokines (IFNγ, IL10, TGFβ) represents important biomarkers of melanoma immune response." (PMID 33810032, 2021). "Briefly, surveillance by T cells leads to recognition of tumor neoantigens as foreign and, upon activation, upregulates PD-1 and secretion of interferon-gamma (IFN-γ)." (PMID 34298809, 2021). "Administration with the 11-bacterium mix (11-mix) recovered efficacy of anti-PD1 or anti-CTLA4 with infiltration with IFNγ+ T cells in MC38 tumor." (PMID 34589427, 2021). "The increase in the cytotoxic capability of CD8 T cells resulted in significantly (p = 0.0026) higher levels of interferon-gamma (IFNγ) mRNA in whole tumor lysates." (PMID 34638488, 2021). "Interferon gamma is known to contribute to tumor immune resistance by inducing the expression of immune checkpoint receptors and their ligands." (PMID 35003017, 2021). "In the tumor microenvironment, the expression of PD-L1 can be markedly upregulated on tumor cells in the presence of interferon-gamma (IFN-γ), while the expression of PD-1 is significantly lifted on tumor-infiltrating lymphocytes." (PMID 34305619, 2021). "Interferon γ (IFNγ) produced by tumor-infiltrating T cells induces signal transducers and activators of transcription 1 (STAT1) activation in tumor cells, promoting HLA-I expression." (PMID 34458148, 2021). "Both CD4+CD8α+ and CD4+CD8αβ+ TEG011 cells secreted significantly higher levels of IFNγ upon exposure to tumor targets than CD4+ TEG011 cells." (PMID 34759930, 2021). "Signal transducer and activator of transcription 1 (STAT1) signaling potentiates antitumor immune responses downstream of type I (IFNα/β) and II (IFNγ) interferons (IFNs), both within tumor cells and immune cells." (PMID 34083537, 2021). "For example, upon antigen recognition, CAR T cells produced proinflammatory cytokines, such as IFNG, which sensitized tumor cells to death receptor-mediated cell death by upregulating FAS expression." (PMID 34771652, 2021). "Subsequent pathway analysis and manual annotation showed a clear upregulation of genes involved in the immune escape of tumor due to IFNγ treatment." (PMID 35003017, 2021). "In this study, we encapsulated T317 in D-Nap-GFFY hydrogel to promote the expression of IFNγ in macrophages for anti-tumor effect." (PMID 33456564, 2021). "In another study, intratumoral NK-derived IFNγ was shown to induce expression of fibronectin 1 in tumor cells, changing the tumor architecture and reducing metastases formation in vivo." (PMID 33801234, 2021). "Strikingly, a large proportion of the IFNγ signature genes were upregulated by SHP2 inhibition specifically in tumor cells in co-culture, including cytokines (CXCL9, CXCL10, CXCL11 and CCL5) and antigen presenting machinery (HLA-A, HLA-B and B2M)." (PMID 33446805, 2021). "IFNγ is a potent promoter of antitumor immunity, inducing M1 macrophage polarization, increased T cell activation, and tumor cell apoptosis." (PMID 34433873, 2021). "We characterized gene expression changes in the IFNγ signaling pathway of tumor cells from scRNAseq data." (PMID 33446805, 2021). "C1QChigh and SPP1low TAMs gene signatures group exhibited enrichment of TCR signaling and interferon gamma signaling, suggesting the anti-tumor functions in these patients." (PMID 34295336, 2021). "In this way interferon gamma can play a critical role in negative regulation of T cell activation through the expression of PD-1 receptors on the tumor cell." (PMID 34268109, 2021). "The tumours were again stratified into low and high hypoxia and in both cohorts the high hypoxia tumours showed significantly higher IFNγ scores compared with the low hypoxia tumours." (PMID 34819027, 2021).
tumor (continued). "Arginase I (ARG1), released by TANs, also participate in supporting NK cell pro-angiogenic features, suppressing NK cell capability to produce anti-tumor factors such as IFNγ." (PMID 34960234, 2021). "Consistently, tumor-infiltrating immune cells of B16-bearing HSD-fed RAG1−/− mice showed a significant up-regulation in IFNγ and a marginal increase in TNFα levels in NK cells." (PMID 34516769, 2021). "T helper 1 (TH1) cells represent a subset of the CD4 + T cell population that typically expresses high levels of interferon gamma, which acts to limit tumor growth, promote antigen presentation and active macrophages M1." (PMID 34952631, 2021). "EOC2 only reduced CD69 and IFNγ protein level on T cells in response to TuCM conditioning combined with tumor cell co‐culture." (PMID 33755340, 2021). "M1 cells are “classically activated” by IFNγ, and destroy tumor cells through their production of nitric oxide and type 1 cytokines and chemokines." (PMID 33535484, 2021). "iNKT cell recruitment of B cells into the TME can enhance T cell responses by in part serving as APCs and presenting tumor antigens, as well as, polarizing lymphocytes towards Th1, Th2 or other functional states by secreting IFNγ and IL-4." (PMID 34680322, 2021). "In conclusion, this study showed that tumor cells of the majority of CRCs display a functional caspase-1/IL-18 axis, part of the inflammasome pathway, that can modulate the IFNγ response elicited by Th1/Tc1 TILs from the tumor microenvironment." (PMID 33430344, 2021). "Th17 cells expressing IFNγ can be tumor-cytolytic, while those expressing immune suppressive cytokine IL-10, promote tumor growth." (PMID 34943886, 2021). "While baseline IFNg is higher in the recurrent tumor, the level of TNFa, RANTES (CCL5), IP-10, IL-5, IL-10, MIP1a (CCL3), MIP1b (CCL4), and GM-CSF are all significantly lower in the recurrent tumor." (PMID 34221953, 2021). "As activated B cells are capable of inducing comparable CTL-produced IFNγ levels and tumor cell death as DCs, vaccines composed of B cells are under investigation." (PMID 33801234, 2021). "They found that the anti-VEGFR2 antibody treatment is associated with lymphocyte homing into the tumor, whereas the anti-PD-L1 antibody induces activation of infiltrated CD4+ and CD8+ T cells that produce IFNγ." (PMID 34572847, 2021). "In particular, it has been described that tumor cells can modulate PD-L1 expression on MDSCs through the release of cytokines such as IFNγ." (PMID 33777750, 2021). "Interferon-gamma (IFN-γ) is a key cytokine involved in cellular immunity and associated with both pro- and anti-tumour activity." (PMID 34944729, 2021). "In one study, researchers demonstrated a correlation between protein homeostasis and tumor antigen presentation by showing IFNγ-independent changes the MHCI peptide repertoire by low-level inhibition of the Heat Shock Protein Hsp90." (PMID 33406696, 2021). "Although the majority of studies have used solid tumor models, the importance of IFNγ in anti-tumor immunity has also been shown in B cell malignancy models." (PMID 33842331, 2021). "Patients who respond to anti-PD-1 therapy exhibit a tumor micro-environment that is enriched for interferon γ (IFNγ) and tumor infiltrating lymphocytes (TILs), the so called ‘hot’ tumors." (PMID 34071888, 2021). "A positive correlation between GSDMD and CD8A, GZMB, and IFNG expression in CTLs was also seen in many other tumor types and in 30 primary tumor samples from patients with NSCLC, further confirming the associations seen from TCGA." (PMID 34429144, 2021). "CD8 TRM cells are primed to secrete large quantities of IFNγ and TNFα following antigen re-exposure in the context of both viral and tumor responses as well as models of autoimmune vitiligo." (PMID 34362825, 2021). "The release of IFNγ into the tumor microenvironment has multiple effects, such as the destruction of tumor vasculature and augmentation of macrophage-mediated killing." (PMID 34201655, 2021).
tumor (continued). "It had been well established that the inflammatory cytokines, such as IFNγ, abundant in the tumor microenvironment, boost tumor cell PD-L1 expression." (PMID 34240739, 2021). "Immunotherapy with anti-PD-1 increases MHC-I expression on IFNγ-sensitive tumor cells in the presence of tumor-reactive T cells." (PMID 34201655, 2021). "For example, IFNγ increases the expression of MHC class I molecules on the surface of tumor cells, enhancing their immunogenicity and, consequently, making them more vulnerable to immune-mediated cell killing." (PMID 33801234, 2021). "In particular, of them, IFNγ is the strongest inducer to elevate PD-L1 expression in tumor microenvironment, known as “adaptive immune resistance”." (PMID 34365463, 2021). "γδ T cells express T-bet and eomesodermin constitutively and so can rapidly differentiate and secrete IFNγ once stimulated with IL-2 and IL-15, promoting anti-tumor immune responses." (PMID 33801234, 2021). "For instance, high levels of interferon gamma, which is regarded as a potent signal for microglia activation, were expressed by tumor-infiltrating CD-8 T cells up to 20 days post treatment." (PMID 33658642, 2021). "Nrp1−/− Tregs found within the TME produce IFNγ, which suppress the function of surrounding wild-type Tregs, increase anti-tumor immune activity." (PMID 33801234, 2021). "IFNg is a critical proinflammatory cytokine for natural and adaptive immunity against viral and intracellular bacterial infections and tumor control." (PMID 33237662, 2021). "IL-12, produced mainly by macrophages and DCs, is thought to be tumor suppressive through its ability to stimulate Interferon-γ (IFNγ) production by Th1 cells and NK cells." (PMID 34901003, 2021). "Here, we show that treatment of WT mice with soluble or exosomal αGC increased IFNγ secretion and degranulation upon receptor stimulation, specifically in educated NK cells ex vivo, and increased tumor rejection in vivo." (PMID 33467442, 2021). "CAR+ cells that express high levels of GZMB RNA or IFNγ RNA can be observed by confocal microscopy close to the residual tumor." (PMID 34155235, 2021). "A major signaling hallmark of responders across cell categories was increased Stat1 expression, indicating a tumor-wide IFNγ response." (PMID 34433873, 2021). "Our team constructed CpG capsuled Cu9S5@mSiO2-PpIX@MnO2 NPs to promote infiltration of CTLs in tumor tissue, and further upregulated interferon gamma (IFN-γ) to promote immune response." (PMID 34062992, 2021). "The survival benefit was accompanied by significant tumor infiltration by granzyme B-, IFNγ-, and TNFα-secreting effector T cells." (PMID 33503832, 2021). "Conversely, MAIT cells can display an exhausted phenotype with reduced capacity to produce anti-tumour cytokines, such as IFNγ and TNFα." (PMID 33808058, 2021). "Intratumoural TNFα injection induced 10% tumour EC apoptosis, and co-treatment with TNFα and IFNγ further increased tumour EC apoptosis to 22%." (PMID 34285232, 2021). "Intriguingly, the authors also found two patient-derived TCRs that were reactive to tumour neoantigens and stimulated production of the effector cytokine IFNγ." (PMID 32457487, 2021). "This inflamed TME has been observed in the setting of tumor-infiltrating CD8+ T cells secreting IFNγ, triggering an intratumoral antitumor inflammatory state." (PMID 35087529, 2021). "NK cells are innate lymphoid cells involved in tumor immunosurveillance by inducing cancer cell lysis both directly (via perforin/granzyme system) or indirectly (via secretion of TNFα and IFNγ)." (PMID 34638439, 2021). "On the other side, cancer models have shown that IL10 also induces intratumoral antigen presentation with infiltration and activation of tumor-specific cytotoxic CD8 T cells expressing IFNγ and granzymes." (PMID 34447383, 2021).
tumor (continued). "Up-regulated expression of programmed death-ligand 1 (PD-L1) by interferon-gamma (IFN-γ) has been associated with promotion of cancer cell survival and tumor cell escape from anti-tumor immunity." (PMID 34500779, 2021). "We find that addition of SBRT extended mouse survival and correlated with increased IFNγ-producing, tumour-specific T cells." (PMID 34784792, 2021). "This impairment was associated with proximity to the tumour, with tumour-margin MAIT cells producing more IFNγ than tumour-infiltrating MAIT cells." (PMID 33808058, 2021). "This adjusted ratio resolves the lower tumor cell lysis and IFNG release by CAR T cells in the bioprinted 3D tumor model compared to 2D cocultures." (PMID 34267756, 2021). "It is reported that the disruption of the CARMA1–BCL10–MALT1 (CBM) signalosome complex and induction of IFNγ secretion suppress Tregs, activate the adaptive immune response, hinder tumor growth, and improve the efficacy of immune checkpoint therapy." (PMID 33968014, 2021). "The effects on TAM survival and polarization were found to be mediated by tumor derived factors, these being IFNγ and GM-CSF." (PMID 34988021, 2021). "Interferon gamma (IFNγ) represents a major driving force behind PD-L1 expression in tumor microenvironment, and histone deacetylase 2 (HDAC2) is required for IFN signaling." (PMID 34365463, 2021). "IFNγ also acts directly on tumor cells, regulating their survival and immunogenicity through multiple mechanisms." (PMID 33801234, 2021). "When vaccinated with P2Et-pretreated 4T1 cells, the primary tumor growth was improved by yielding IL-2, TNFα, IL-4, IL-5, and IFNγ-producing CD4+ and CD8+ T lymphocytes." (PMID 34948368, 2021). "Interferon-gamma (IFNG) has profound impacts on tumor-immune interaction and is of great clinical significance for multiple cancers." (PMID 34566988, 2021). "We found that the co-culture of tumor cells stimulated the increase of granzyme B and IFNγ in CD8+ T, but A549 exhibited resistance against CD8+ T cytotoxicity compared to HCC827." (PMID 34685495, 2021). "The release of IFNγ by CD8+ T cells is similarly affected by location of T cell entry point; however, its concentration is higher at the invasive front as shown in case B, which has higher IFNγ concentration compared to the core of tumor from case A." (PMID 34359653, 2021). "Interferon-gamma (IFNγ) is an important pro-inflammatory cytokine that functions in immune and inflammatory responses and in tumour immunosurveillance and homeostasis." (PMID 34193146, 2021). "Inhibition of SHP2 activity augmented tumor intrinsic IFNγ signaling resulting in enhanced chemoattractant cytokine release and cytotoxic T cell recruitment, as well as increased expression of MHC Class I and PD-L1 on the cancer cell surface." (PMID 33446805, 2021). "IFNγ strongly promotes inflammatory responses and has been shown to augment the function of tumor-infiltrating immune cells including CD4+ TH1 cells, CD8+ T cells, dendritic cells and macrophages, while suppressing TH2 cells and Tregs." (PMID 33842331, 2021). "Both IFNI and IFNγ drive polarization of CD4+ T cells towards the anti-tumor Th1 phenotype, preventing differentiation into the protumor Th2 phenotype." (PMID 33801234, 2021). "PDL1 on the surface of tumor cells can be upregulated by interferon gamma (IFN-γ) produced by activated T cells." (PMID 34539412, 2021). "CD276 is a strong immunosuppressive checkpoint that is highly expressed in numerous solid tumors, which promotes the immune escape of tumor cells from the cytotoxic effects of interferon-gamma (IFN-γ) and tumor necrosis factor-alpha (TNF-α)." (PMID 35052695, 2021). "For example, IFNγ can upregulate immune checkpoint molecules such as PD-L1, which enhances tumor immune evasion." (PMID 33849634, 2021). "In contrast, IFNγ stimulation can increase tumor growth and accelerate the formation of 5tumor immunosuppressive microenvironment." (PMID 35126382, 2021).